EGFR (epidermal growth factor receptor)
Diseases named in the same sentence as EGFR in open-access papers (continued):
Sharing a sentence is not in itself a finding about the gene and the disease.
non-small cell lung carcinoma (continued). "Activating EGFR mutation represents one of the key driver oncogenes in patients with non-small cell lung cancer." (PMID 33621951, 2021). "This has been well highlighted in non-small cell lung cancer, where ctDNA can be used to observe epidermal growth factor receptor (EGFR) targetable mutations in the primary tumour, reducing the need for tissue sampling." (PMID 33494364, 2021). "Several studies have demonstrated that non-small cell lung cancer patients (NSCLCs) harboring epidermal growth factor receptor (EGFR) mutations have poor clinical outcomes in response to treatment with programmed death-1 (PD-1) inhibitors." (PMID 32705363, 2021). "Strikingly, EGFR mutations are present in 30–50% of non-small cell lung cancers and these mutations are associated with a favorable response to EGFR tyrosine kinase inhibitors." (PMID 34768773, 2021). "In recent years targeting EGFR has shown some promise; indeed, EGFR is implicated in a variety of cancers including non-small cell lung cancer, colorectal cancer, pancreatic cancer, and head and neck squamous cell carcinoma (HNSCC)." (PMID 34122442, 2021). "The most negatively correlated drug was afatinib, a small molecule approved by the Food and Drug Administration (FDA) for the first-line treatment of non-small cell lung cancer with EGFR mutations." (PMID 34200770, 2021). "Epidermal growth factor receptor (EGFR) tyrosine kinase inhibitors (TKIs) significantly improve the outcome of non-small-cell lung cancer (NSCLC) patients with EGFR mutations, however, most TKI-treated patients will develop resistance to TKIs." (PMID 33758606, 2021). "The EGFR T790M mutation in non-small cell lung cancer is a resistance mutation for molecularly targeted drugs and has been shown to be useful in selecting other drugs." (PMID 33249514, 2021). "Structural classification of mutations in the epidermal growth factor receptor causing non-small cell lung cancer is a better predictor of patient outcomes following drug treatment than traditional exon-based classification." (PMID 34526717, 2021). "Non-small cell lung cancers (NSCLCs) harboring activating mutations in the epidermal growth factor receptor (EGFR) tyrosine kinase domain are typically treated with EGFR tyrosine kinase inhibitors." (PMID 33804833, 2021). "For example, the treatment of EGFR mutated non-small-cell lung cancers with EGFR inhibitors like erlotinib improved patients outcome significantly and is nowadays standard of care." (PMID 33862582, 2021). "Quercetin is an effective inhibitor for the treatment of non-small-cell lung cancer harboring the EGFR C797S mutation." (PMID 34572484, 2021). "To assess the adequacy and efficacy of the IdyllaTM system in testing EGFR mutations in cytological specimens of non-small-cell lung cancer (NSCLC), we reviewed the international literature identifying 4 articles describing 471 cases." (PMID 34063720, 2021). "On the other hand, EGFR kinase domain activating point mutations are associated with non-small cell lung carcinoma and glioblastoma, but are rarely seen in other types of cancer." (PMID 34096503, 2021). "The most promising responses were seen in HER2-positive breast cancer and in non-small cell lung cancer (NSCLC) patients with ALK translocations or EGFR mutations." (PMID 34077750, 2021). "Exploring mechanisms of drug resistance to targeted small molecule drugs is critical for an extended clinical benefit in the treatment of non-small cell lung cancer (NSCLC) patients carrying activating EGFR mutations." (PMID 33804833, 2021). "This study aims to estimate the frequency of Epidermal Growth Factor Receptor mutations in Iraqi patients with Non-Small Cell Lung Cancer." (PMID 33639678, 2021). "Osimertinib is the standard treatment of advanced epidermal growth factor receptor (EGFR)-mutated non-small cell lung cancer (NSCLC) patients and EGFR T790M-mediated resistance." (PMID 33919291, 2021).
non-small cell lung carcinoma (continued). "For patients receiving carboplatin-paclitaxel for chemo-naïve non-small cell lung cancer with sensitive EGFR gene mutations, the respective 1- and 2-year survival NEJ002 (CBDCA/PTX) was 86.8% and 53.7%." (PMID 34452564, 2021). "leveraged the threshold of a predefined model to detect EGFR mutations in non-small cell lung cancer, achieving a higher sensitivity than that of ctDNA detection alone." (PMID 34367974, 2021). "It is used for the treatment of locally advanced or metastatic non-small cell lung cancer (NSCLC) patients with sensitive mutations of EGFR." (PMID 33391438, 2021). "For the treatment of EGFR-mutated advanced non-small cell lung carcinoma (NSCLC), gefitinib (250 mg) was prescribed once a day." (PMID 33640029, 2021). "Patients with non-small cell lung cancer (NSCLC) with epidermal growth factor receptor (EGFR) mutations exhibit an unfavorable response to PD-1 inhibitor through unclear mechanisms." (PMID 34663810, 2021). "Epidermal growth factor receptor (EGFR) mutations are the most commonly observed mutations in non-small cell lung cancer and EGFR tyrosine kinase inhibitors (gefitinib and erlotinib) are used as the primary treatment." (PMID 34683198, 2021). "This would allow for the first time the easy and fully automatic assessment of EGFR mutation detection from plasma of non-small cell lung cancer patients." (PMID 33935776, 2021). "Based on the current available evidence, patients of non-small cell lung cancer with brain metastases and EGFR mutations have better OS and iPFS (intracerebral progression free survival) when they receive up-front radiotherapy and TKI than TKI alone." (PMID 33435596, 2021). "Resistance to tyrosine kinase inhibitors (TKIs) that target common non-small-cell lung cancer mutations within the epidermal growth factor receptor (EGFR) is a primary clinical issue." (PMID 34572879, 2021). "Upon review of the epidemiological data in the Asian population, 40-55% of patients with non-small cell lung cancer were found to harbor EGFR mutations." (PMID 33828971, 2021). "Epidermal growth factor receptor tyrosine kinase inhibitors (EGFR-TKIs), such as gefitinib, have achieved good efficacy in EGFR mutation-positive non-small-cell lung cancer (NSCLC) patients, but eventual drug resistance is inevitable." (PMID 34332557, 2021). "The discovery of epidermal growth factor receptor oncogenic driver mutations has changed the therapeutic landscape of advanced non-small cell lung cancer in the past decade." (PMID 34809713, 2021). "The studies presented herein were driven by reports demonstrating that EGFR mutations are associated with low response rates to PD-1 pathway blockade in non-small cell lung carcinoma (NSCLC)." (PMID 34038737, 2021). "In advanced stages of non-small cell lung cancer, EGFR and ALK mutations predict a better prognosis and sensitivity to target therapy." (PMID 33921579, 2021). "Epidermal growth factor receptor-tyrosine kinase inhibitors (EGFR-TKIs) have shown marked efficacy in non-small cell lung cancer (NSCLC) patients with EGFR mutations." (PMID 33924522, 2021). "Case presentation: We treated a 67-year-old female diagnosed with non-small-cell lung cancer with an EGFR 21 exon L858R-positive mutation." (PMID 34366844, 2021). "EGFR-activating mutations, such as exon 19 deletion or the L858R mutation in exon 21, occur in 10–15% of patients with non-small cell lung cancer." (PMID 34298655, 2021). "Afatinib is used to treat non-small-cell lung cancer (NSCLC) harboring epidermal growth factor receptor (EGFR) mutation as a second-generation EGFR-tyrosine kinase inhibitor (TKI)." (PMID 34298637, 2021). "Previous bioinformatic analyses showed that hsa-miR-30d-3p was associated with non-small cell lung cancer and inhibited epidermal growth factor receptor-targeted medicine therapy." (PMID 34336929, 2021).
non-small cell lung carcinoma (continued). "To further demonstrate higher ctDNA content in fraction 6, we performed mutational analysis in the plasma samples from 22 non-small cell lung cancer (NSCLC) patients with known EGFR mutations." (PMID 34178690, 2021). "Activating mutations in the kinase domain of the epidermal growth factor receptor (EGFR) drive the growth of 10–30% of non-small cell lung cancers (NSCLCs), the leading cause of cancer mortality worldwide with a five-year survival rate of 23%." (PMID 34359849, 2021). "The most robust study of the anticancer activity of PT against lung cancer to date examined PT in combination with Osimertinib against five EGFR-mutation positive non-small cell lung cancer (NSCLC) cell lines." (PMID 33801098, 2021). "Epidermal growth factor receptor (EGFR) tyrosine kinase inhibitors (TKIs) show robust efficacy for EGFR mutation-positive non-small-cell lung cancer (NSCLC)." (PMID 34298637, 2021). "Tyrosine kinase inhibitors (TKIs) have significant efficacy in patients with advanced non-small cell lung cancer (NSCLC) with activating epidermal growth factor receptor (EGFR) mutations." (PMID 34766562, 2021). "The reported radiographic response rates in patients with non-small-cell lung cancer with EGFR exon 20 insertion mutations range from less than 15% for poziotinib to close to 30% for mobocertinib but the duration of response can exceed 15 months." (PMID 34944068, 2021). "Amivantamab was recently granted accelerated approval by the FDA for patients affected by non-small cell lung cancer (NSCLC) harboring exon 20 insertion mutation in EGFR gene, with disease progression on/after platinum-based chemotherapy." (PMID 34577584, 2021). "Non-small cell lung cancer models that harbour EGFR mutations and ALK rearrangements have demonstrated induction of PD-L1 expression and reduction of PD-L1 when treated with targeted therapies such as EGFR and ALK inhibitors." (PMID 33956842, 2021). "EGFR overexpression is associated with the development of epithelial malignancies, such as non-small cell lung cancer, ovarian cancer, colorectal cancer and prostate cancer." (PMID 32989604, 2020). "Mutations in EGFR lead to its overexpression, which results in its constant activation and uncontrolled cell division in many different cancers (e.g., non-small cell lung cancer (NSCLC), colorectal cancer, pancreatic cancer, etc.)." (PMID 32916883, 2020). "The first EGFR tyrosine kinase inhibitor (TKI) was approved for clinical use in 2003 and was mostly used in patients with non-small-cell lung cancer (NSCLC) carrying EGFR-activating mutations and in patients with breast and pancreatic cancers." (PMID 33574751, 2020). "The tests are used to identify the non-small cell lung cancer patients with epidermal growth factor receptor (EGFR) gene mutations." (PMID 33614495, 2020). "A MSA, capable of detecting mutations in the epidermal growth factor receptor (EGFR) gene directly in saliva samples, was proposed to identify epithelial cancers, particularly non-small cell lung carcinoma." (PMID 32585936, 2020). "EGFR TKI therapy has become a first-line regimen for non-small cell lung cancer (NSCLC) patients with EGRF mutations." (PMID 32483443, 2020). "The objective of this study was to apply the approach of Doble & Lorgelly for validation of existing mappings to EGFR mutation-positive non-small cell lung cancer (NSCLC) instead of a mixed cohort of cancers." (PMID 32319016, 2020). "These genes are frequently mutated in non-small cell lung cancer (NSCLC) with variable frequencies: EGFR, ALK; ROS1 and RET." (PMID 32928143, 2020). "Treatment naïve, advanced non-small-cell lung cancer patients with EGFR-sensitizing mutation received afatinib monotherapy." (PMID 32028909, 2020).
non-small cell lung carcinoma (continued). "For example, non-small cell lung cancer (NSCLC) cells harboring the T790M mutations in the Epidermal Growth Factor Receptor (EGFR) are resistant to the cancer drug, gefitinib, whereas cells harboring the L858R mutation are hypersensitive to the same drug." (PMID 33183223, 2020). "The prevalence of Skeletal Related Adverse Events (SREs) in EGFR mutated non-small cell lung cancer (NSCLC) patients with bone metastases, treated with modern tyrosine kinase inhibitors (TKIs), has been scarcely investigated." (PMID 33282740, 2020). "Erlotinib is an FDA-approved agent for the treatment of epidermal growth factor receptor (EGFR)-mutated non-small cell lung cancer (NSCLC), and pancreatic cancer." (PMID 32351709, 2020). "Several studies showed that IFITM1 critically regulates epidermal growth factor receptor-mediated signaling in non-small cell lung cancer models and is associated with a poor prognosis of patients with adenocarcinoma." (PMID 33585210, 2020). "Correct identification of the EGFR c.2369C>T p.(Thr790Met) variant is key to decide on a targeted therapeutic strategy for patients with acquired EGFR TKI resistance in non-small cell lung cancer." (PMID 32357863, 2020). "Osimertinib is able to increase the phosphorylation of AXL in EGFR-mutated non-small cell lung cancer (NSCLC) cells, which subsequently activate HER3, MET, EGFR and the corresponding downstream signals." (PMID 32171304, 2020). "One re-biopsy sample showed an activating CTNNB1 mutation, which is reported to confer resistance to EGFR therapies in non-small cell lung cancer." (PMID 32397977, 2020). "Targeted therapies and, more precisely, EGFR tyrosine kinase inhibitors (TKIs) have been a major improvement in the therapeutic management of EGFR-mutated non-small-cell lung cancers (NSCLCs)." (PMID 32751202, 2020). "Activating mutations of epidermal growth factor receptor (EGFR) are one of the most common oncogenic drivers in non-small cell lung cancer (NSCLC) and are detected in approximately 40% of East Asian patients and 15% of Caucasian patients." (PMID 33396393, 2020). "ctDNA is commonly used to identify mutations in the EGFR gene in non-small cell lung cancer (NSCLC), when tumour tissue cannot be sampled or when its analysis is not contributive." (PMID 32664549, 2020). "Tyrosine kinase inhibitor- (TKI-) based therapy revolutionized the overall survival and the quality of life in non-small-cell lung cancer (NSCLC) patients that have epidermal growth factor receptor (EGFR) mutations." (PMID 32256580, 2020). "The drugs are registered for the treatment of adenocarcinoma of non-small cell lung cancer (NSCLC) with activating EGFR mutations." (PMID 33182766, 2020). "The discovery of epidermal growth factor receptor (EGFR) mutation and the introduction of EGFR-tyrosine kinase inhibitors (EGFR-TKIs) have revolutionized the treatment strategy for non-small-cell lung cancer (NSCLC) harboring EGFR-sensitizing mutations." (PMID 32796633, 2020). "No study has yet comprehensively evaluated the prevalence of epidermal growth factor receptor (EGFR) mutation characteristics in patients with non-small cell lung cancer (NSCLC) in Xuanwei." (PMID 33224870, 2020). "Third-generation epidermal growth factor receptor (EGFR) tyrosine kinase inhibitors (TKIs) were developed to target the EGFR T790M resistance mutation in non-small cell lung cancer (NSCLC) patients resistant to first- or second-generation EGFR-TKIs." (PMID 31959859, 2020). "EGFR is a receptor tyrosine kinase that is somatically mutated in 10% of non-small cell lung cancers." (PMID 32357859, 2020). "EGFR mutations that confer sensitivity to tyrosine kinase inhibitors (TKI) in non-small cell lung carcinomas paved the way for a precision medicine approach in this neoplastic form." (PMID 32215186, 2020).
non-small cell lung carcinoma (continued). "In 2016, the Food and Drug Administration (FDA) firstly approved the use of ctDNA as a liquid biopsy test for patients with stage IV non-small cell lung cancer (NSCLC) to check for epidermal growth factor receptor (EGFR) mutations." (PMID 33339259, 2020). "Both EGFR mutations and amplifications are a driving force behind many cancers including breast, non-small cell lung carcinoma (NSCLC), glioblastoma, head and neck squamous cell carcinoma (HNSCC), ovarian and melanoma." (PMID 33143170, 2020). "The results of the AURA3 trial, a phase III trial comparing osimertinib with platinum and pemetrexed for patients with non-small cell lung cancer (NSCLC) harboring the EGFR T790M mutation who were previously treated with EGFR-TKIs, were reported in 2017." (PMID 32357848, 2020). "In patients with metastatic non-small-cell lung cancer, for example, testing for EGFR mutations and ALK rearrangements, among other alterations, is critical for selecting the appropriate systemic therapy." (PMID 32637176, 2020). "Of enormous scientific interest has been the discovery of somatic driver mutations in this malignancy, with up to 10 and 4% of non-small cell lung cancers carrying epidermal growth factor receptor mutations and ALK translocations, respectively." (PMID 33272232, 2020). "In non-small-cell lung cancer, mutation of epidermal growth factor receptor (EGFR) stimulates cell proliferation and survival." (PMID 32179851, 2020). "The current study focuses on comparing the mutation detection efficiency of High-Resolution Melt Analysis (HRM) with Sanger Sequencing in somatic mutations of the EGFR gene in non-small cell lung cancer." (PMID 32962681, 2020). "It was known that lung adenocarcinoma can be transformed into neuroendocrine carcinoma under epidermal growth factor receptor (EGFR)-tyrosine kinase inhibitor (TKI) treatment, leading to resistance in EGFR-mutated non-small-cell lung cancers." (PMID 32380703, 2020). "Epidermal growth factor receptor (EGFR) activating mutations play crucial roles in the tumorigenesis of human non-small cell lung cancer (NSCLC)." (PMID 32276600, 2020). "These genetic insights have helped to develop new diagnostic and targeted therapeutic tools; as an example, mutation(s) in the epidermal growth factor receptor (EGFR) is frequently observed in non-small cell lung cancer (NSCLC) patients." (PMID 32580362, 2020). "Epidermal growth factor receptor (EGFR) tyrosine kinase inhibitors (TKIs) are the standard first-line therapy for advanced non-small cell lung cancer (NSCLC) patients harboring EGFR-sensitizing mutations." (PMID 32854745, 2020). "Several studies in non-small-cell lung cancer have already shown the ineffectiveness of ICI in the case of tumors with EGFR mutations and low TMB." (PMID 32825510, 2020). "Activating mutations in the epidermal growth factor receptor underlying responsiveness of non-small-cell lung cancer to gefitinib.." (PMID 32308931, 2020). "Epidermal growth factor receptor (EGFR) mutations are common in non-small cell lung cancers, but rare in small cell lung cancers (SCLCs)." (PMID 32766137, 2020). "The EGFR C797S mutation represents a major challenge for treatment of osimertinib-resistant tumors in non-small cell lung cancer." (PMID 33133066, 2020). "Reportedly, EGFR overexpression or mutation plays an important role in tumorigenesis in various types of epithelial cancers, including non-small-cell lung cancer, breast cancer, colorectal cancer, and gastric carcinoma." (PMID 32695675, 2020). "In recent, some reports announce that erlotinib or other EGFR inhibitors cause HBV reactivation in patients with advanced non-small-cell lung cancer in the context with positive HBsAg." (PMID 32322693, 2020). "Targeted drugs represented by epidermal growth factor receptor (EGFR) tyrosine kinase inhibitors (EGFR-TKIs) have shown great benefits in EGFR-mutated non-small-cell lung cancer (NSCLC) in recent years." (PMID 32477939, 2020).